EZH2 (enhancer of zeste 2 polycomb repressive complex 2 subunit)
Diseases named in the same sentence as EZH2 in open-access papers (continued):
Sharing a sentence is not in itself a finding about the gene and the disease.
metastatic melanoma (10 papers, 2012 to 2024). A melanoma that has spread from its primary site to another anatomic site. "The G1-S transition-regulating transcription factor EZH2 has been implicated in downregulation of some cilia-related genes and decreased ciliation, also termed cilia deconstruction, in cycling metastatic melanoma cells." (PMID 39705308, 2024). "Moreover, EZH2 also interacted with sex and had a significant association with survival in patients with primary or metastatic melanoma and overall SKCM cohort (interaction p = 0.045, 0.049, 0.02 respectively)." (PMID 32731355, 2020). "In clinical samples, EZH2 increased during disease evolution from benign nevus to metastatic melanoma." (PMID 36906655, 2023). "It was also suggested that EZH2 is required for efficient lung and lymph node colonization by metastatic melanoma." (PMID 36906655, 2023). "H3K27me3 and EZH2 expression were evaluated in a cohort of 44 metastatic melanoma samples before ICB using immunohistochemistry (IHC)." (PMID 32041674, 2020). "Interestingly, a mild decline (p = 0.0575) was noted in cytosolic UBE2L6 from early stage to metastatic melanoma, inversely correlated with EZH2." (PMID 36906655, 2023). "The higher expression of DNMT1 and EZH2 is concordant with previous observations in BRAF-mutated cells, such as it is the case for WM266-4, described to participate in the hypermethylated phenotype of metastatic melanoma cells (and personal observations)." (PMID 30651148, 2019). "We found the expression of EZH2 to be low or absent in benign nevi, and EZH2 expression displayed progressive increase from benign nevi, dysplastic nevi, localized and metastatic melanoma samples (p-value =0.0015, =1.7E-16, =0.05 respectively)." (PMID 22948084, 2012).
multiple sclerosis (10 papers, 2016 to 2026). A progressive autoimmune disorder affecting the central nervous system resulting in demyelination. "The aggregate results from the study suggest a role for EZH2 in the migration of T cells into the CNS in patients with multiple sclerosis and also suggest a potential pathogenic capacity of EZH2-positive T cells that will need to be explored more in depth in future studies." (PMID 30367633, 2018). "More specifically, EZH2 has been shown to exacerbate demyelination in multiple sclerosis while it can support neuroprotection and repair in stroke recovery." (PMID 40723311, 2025). "In this latter study, loss of EZH2 reduced inflammatory responses to stimulus and so reduced disease severity, pointing the way to pharmacological inhibition of EZH2 as a therapeutic strategy in multiple sclerosis." (PMID 34464475, 2021). "We next investigated the expression levels of miR-124 and miR-155, two microRNAs that are known on the one hand to target EZH2 and on the other hand to be involved in multiple sclerosis." (PMID 30367633, 2018). "In the search for potential microRNAs that on the one hand regulated EZH2 expression and on the other hand were involved in multiple sclerosis, the microRNAs miR-124 and miR-155 emerged as attractive candidates." (PMID 30367633, 2018). "Confirmation of the migratory capacity of EZH2-positive T cells was provided by their detection in the CSF and brain lesions from multiple sclerosis patients." (PMID 30367633, 2018). "The decreased expression of EZH2 in PBMC from patients with multiple sclerosis was replicated in an independent validation cohort of patients and controls." (PMID 30367633, 2018). "As a last step, we incubated in vitro PBMC from seven untreated multiple sclerosis patients with an EZH2 inhibitor in order to investigate the genes modulated by EZH2 and aiming to better understand the role of EZH2 in disease pathophysiology." (PMID 30367633, 2018). "Although EZH2 expression in brain lesions from multiple sclerosis patients seemed restricted to CD4+ and CD8+ T cells, additional sources of EZH2 expression within the CNS cannot be totally ruled out, as evidenced by EZH2 immunohistochemistry." (PMID 30367633, 2018). "Further stratification of the multiple sclerosis group into the different clinical forms revealed significantly decreased gene expression levels of EZH2, TLN1, and VAV1 in PBMC from RRMS, SPMS, and PPMS patients compared to HC." (PMID 30367633, 2018). "We next aimed to extrapolate these findings to patients with multiple sclerosis by determining EZH2 expression in CSF cells from three untreated patients." (PMID 30367633, 2018). "Similarly, in multiple sclerosis, reduced EZH2 expression in circulating CD4+ and CD8+ T cells of untreated patients has been reported, further emphasising the importance of EZH2 in immune regulation." (PMID 41518566, 2026). "Meanwhile, mesenchymal stem cell-derived exosomal miR-367-3p could restrain EZH2 expression to suppress ferroptosis in multiple sclerosis (MS)." (PMID 39518098, 2024). "Disrupting the interactions between EZH2 and Vav1 formed frequent, enlarged focal adhesions that were connected to stress fibers in DCs, impairing the transendothelial migration and restricting multiple sclerosis progression." (PMID 35281921, 2022). "A trend towards decreased expression of EZH2 (p = 0.07) was observed in terminally differentiated effector CD4+ T cells from untreated multiple sclerosis patients compared to HC, and EZH2 expression was significantly upregulated in patients by the effect of natalizumab treatment (p = 0.03)." (PMID 30367633, 2018). "Recent studies in experimental autoimmune encephalomyelitis, an animal model of multiple sclerosis (MS), suggest an involvement of the histone methyltransferase enhancer of zeste 2 polycomb repressive complex 2 subunit (EZH2) in important processes such as cell adhesion and migration." (PMID 30367633, 2018).
multiple sclerosis (continued). "EZH2 findings were validated in an independent cohort of 13 untreated multiple sclerosis patients and 12 HC, and mRNA expression levels for EZH2 were again found to be significantly decreased in PBMC from the multiple sclerosis group compared to the HC group (p = 0.01)." (PMID 30367633, 2018). "Moreover, it is interesting to see that EZH2 and H3K27me3 both top rank in multiple sclerosis and ulcerative colitis as EZH2 represses gene transcription by mediating H3K27me3 methylation." (PMID 27923386, 2016). "Since EZH2 regulates inflammatory gene expression, its levels or activity could also differ between males and females during neurodegenerative diseases like Alzheimer’s or multiple sclerosis." (PMID 40723311, 2025). "Of note, EZH2-positive cells both in CD4+ and CD8+ T cells may have pathogenic potential through the secretion of TNF-α, a pro-inflammatory cytokine involved in the pathogenesis of multiple sclerosis." (PMID 30367633, 2018). "Expression levels for EZH2, TLN1, and VAV1 were significantly decreased in PBMC from the whole multiple sclerosis group compared to controls." (PMID 30367633, 2018). "In this line, we finally investigated EZH2 expression in chronic active lesions from 10 multiple sclerosis patients and observed that 8.5% (mean percentage) and 10.9% of the total CD4+ and CD8+ T cells were expressing EZH2 respectively." (PMID 30367633, 2018). "In order to characterize the PBMC populations that express EZH2, immunophenotyping for EZH2 and flow cytometry analysis was performed in T cells (CD3+, CD4+, and CD8+), B cells, monocytes, and NK cells from 10 multiple sclerosis patients and 13 HC." (PMID 30367633, 2018). "Similar to the mRNA expression findings observed in the whole PBMC population, the percentage of EZH2-positive cells in CD4+ and CD8+ T cells was significantly reduced in untreated multiple sclerosis patients compared to controls." (PMID 30367633, 2018). "Despite this initial publication in the animal model of multiple sclerosis, to date, there are no studies of EZH2 in patients with multiple sclerosis." (PMID 30367633, 2018). "As a next step, we investigated whether EZH2 and TLN1 expression was modulated by commonly used multiple sclerosis therapies." (PMID 30367633, 2018).
anaplastic thyroid carcinoma (9 papers, 2017 to 2026). "Anaplastic thyroid cancer (ATC) lacks iodide uptake ability due to MAPK activation increasing the expression of the histone methyltransferase EZH2, which represses thyroid differentiation genes (TDGs) such as the sodium iodide symporter (NIS)." (PMID 41147659, 2026). "Multiple studies have shown the association of the mutation and overexpression of EZH2 with the development of several types of cancer; for instance, EZH2 overexpression assumes an essential role in anaplastic thyroid cancer." (PMID 35668081, 2022). "Histone methylation modifiers, such as enhancer of zeste homolog 2 (EZH2), have been shown to be overexpressed in anaplastic thyroid carcinoma cells, suppressing PAX-8 transcription." (PMID 33543394, 2021). "We show that anaplastic thyroid carcinoma exhibits an elevated expression of EZH2, and its inhibition through either CRISPR/Cas9-induced EZH2 gene editing or with EPZ6438 inhibitor improves thyroid follicular-cell differentiation and induces mesenchymal–epithelial transition." (PMID 37175580, 2023). "For instance, anaplastic thyroid carcinoma tissues were observed to have overexpressed EZH2." (PMID 35668081, 2022). "In the context of anaplastic thyroid carcinoma (ATC), the inhibition of EZH2 has been demonstrated to suppress Wnt/β-catenin signalling, thereby contributing to its oncogenic role, with targeting EZH2 resulting in reduced β-catenin activity and consequential effects on proliferation and invasion." (PMID 39236081, 2024).
colorectal tumor (9 papers, 2006 to 2023). "Typically, spontaneous colorectal tumors derived from UTX-deficient intestines or human CRC organoids with low UTX expression exhibited sensitivity to EZH2 inhibitors, consistent with previous reports in other cancer types." (PMID 37679762, 2023). "We conducted this study to clarify the association of EZH2 expression with miR-31 and epigenetic alterations using a database comprising more than 500 colorectal tumors." (PMID 26871294, 2016). "We performed this study to identify the association of EZH2 expression with molecular alterations in colorectal tumors." (PMID 26871294, 2016). "They proved that EZH2 is upregulated in colorectal tumor tissues by qRT-PCR and western blot analysis." (PMID 37940644, 2023). "MiR-506 significantly reduced colorectal tumor cell proliferation and migration by EZH2 targeting and WNT signaling regulation." (PMID 37051101, 2023). "In this study, the tissue expressions of lncRNA MINCR and EZH2 mRNA between colorectal tumors and polyps were compared with the adjacent normal tissues collected from 114 Iranian patients, using real-time PCR method." (PMID 34923811, 2022). "In addition, immunohistochemistry analyses revealed that EZH2 was upregulated in colorectal tumor tissues, whereas KLF2 and CDKN2B expression was reduced in cancer tissues." (PMID 30266084, 2018). "EZH2 expression levels are often elevated in colorectal tumors." (PMID 27634879, 2016). "Colorectal cell lines showed SIRT1, EZH2, PCAF underexpression and SUV39H1 overexpression compared to colorectal tumours." (PMID 16638127, 2006).
endothelial dysfunction (9 papers, 2016 to 2025). In vascular diseases, endothelial dysfunction is a systemic pathological state of the endothelium (the inner lining of blood vessels) and can be broadly defined as an imbalance between vasodilating and vasoconstricting substances produced by (or acting on) the endothelium. "Such S-nitrosylation dependent regulation of EZH2 contributed towards NO-driven gene expression changes and endothelial migration as well as reversed endothelial dysfunction in diabetic settings." (PMID 40289112, 2025). "All these data demonstrated that ANRIL plays an important role in mitochondrial injury and endothelial dysfunction through recruiting EZH2 to the promoter region of BDNF." (PMID 35906216, 2022). "As such, disturbances in this reciprocity leading to increased EZH2 expression can induce endothelial dysfunction and EndMT." (PMID 34493753, 2021). "A previous study has reported that S-adenosylhomocysteine (SAH) can trigger the activation of NF-κB pathway to induce endothelial dysfunction and activation, by partially inhibiting the enzymatic activity of EZH2." (PMID 33794893, 2021). "We next investigated whether the EZH2-H3K27me3-driven oxidative phenotype contributes to high glucose-induced endothelial dysfunction." (PMID 38580969, 2024). "On the other hand, in case of low or absent FSS, e.g., in atheroprone arterial regions, high expression of EZH2 could contribute to endothelial dysfunction, e.g., by releasing endothelial cells from quiescence and promoting their (excessive) proliferation." (PMID 26416763, 2016). "Therefore, an altered miRNA-101/EZH2-ß ratio could contribute to the endothelial dysfunction observed in GDM." (PMID 36057662, 2022). "Our results indicate that ANRIL directly binds to EZH2, and mediates BDNF promoter methylation through recruitment of EZH2 to the BDNF promoter region, eventually resulting in endothelial dysfunction." (PMID 35906216, 2022). "We discuss the contribution of endothelial inflammatory activation and dysfunction to atherogenesis and postulate that the dysregulation of specific epigenetic enzymes, EZH2 and SIRT1, aggravate endothelial dysfunction in a pleiotropic fashion." (PMID 33562658, 2021).
ependymoma (9 papers, 2016 to 2025). A WHO grade II, slow growing tumor of children and young adults, usually located intraventricularly. "The study found that miR-17-5p, miR-19a-3p, and miR-106b-5p expressions can effectively differentiate between grade II and III ependymoma tumors and significantly correlate with EZH2 expression." (PMID 37345170, 2023). "EZH2 was recently suggested as the marker of a poor prognosis in children with infratentorial ependymoma." (PMID 27390862, 2016). "We speculate that PFA-ependymomas that express high levels of EZHIP will also exhibit differential sensitivity to EZH2 inhibitors." (PMID 31086175, 2019). "Future studies will explore whether PFA ependymomas exhibit differential sensitivity to EZH2 inhibitors, and whether “detoxification” strategies may exist for EZHIP." (PMID 31086175, 2019). "Because of its connection with epigenetic regulation through PRC complex up-regulation of EZH2 could be considered as the discriminator of PFA ependymomas." (PMID 27390862, 2016). "Correlation analysis of miR-19a, miR-17-5p, miR-106b revealed that their expression levels were significantly correlated with EZH2 expression, suggested marker of PFA ependymomas." (PMID 27390862, 2016). "The few PFA ependymomas that do not overexpress EZHIP appeared to harbor K27M mutations in H3.1 or H3.3, which also inhibit EZH2." (PMID 37085539, 2023). "Other proposed prognostic molecular markers of ependymomas include TERT and EZH2 expression." (PMID 30514397, 2018). "The EZH2 inhibitor GSK343 did not induce a significant reduction in viability for the majority of ependymoma cells tested." (PMID 30559935, 2018).
fibrosis (9 papers, 2014 to 2026). the formation of excess fibrous connective tissue in an organ or tissue in a reparative or reactive process. "Early In Vivo Proof of Concept Data Shows 3-wk Liver-specific Overexpression of EZH2 in Aged Mice Livers Reversed About 8 mo’ Worth of Aging-Associated Global Gene Expression, Steatosis, Fibrosis, and Impaired Glucose Tolerance." (PMID 41512022, 2026). "EZH2 acts as an epigenetic regulator in the progression of cardiac fibrosis through the Smad signaling pathway." (PMID 36552599, 2022). "The lncRNA nuclear enriched abundant transcript 1 (Neat1) promotes cardiac fibrosis in HF through the increased recruitment of EZH2 to the Smad7 promoter region." (PMID 36552599, 2022). "EZH2 has also been documented to be involved in the pathological process of hepatic fibrosis by regulating hepatic stellate cells." (PMID 35264108, 2022). "Mechanistically, bioinformatics analysis showed that miR-101 binds the EZH2 3′UTR and directly reduces EZH2 expression, indicating that miR-101 overexpression could be used in anti-fibrosis clinical application." (PMID 34859108, 2021). "EZH2 may drive hepatic fibrosis via H3K27me3 in order to repress anti-fibrotic gene expression." (PMID 39408226, 2024). "All these results imply that Neat1 promotes cardiac fibrosis by recruiting EZH2, without affecting the EZH2 expression level." (PMID 34980170, 2022).
laryngeal carcinoma (9 papers, 2014 to 2024). Carcinoma that arises from the laryngeal epithelium. "Laryngeal cancers often overexpress EZH2, a histone methyltransferase that is a part of the Polycomb repressive complex 2 (PRC2)." (PMID 39452555, 2024). "In the case of laryngeal carcinoma, targeting EZH2 and other histone methyltransferases is one possible treatment approach." (PMID 39452555, 2024). "In the context of EBV, associated primarily with laryngeal cancer, the high expression of lncRNA H19 in EBV-positive individuals is significantly correlated with the occurrence of laryngeal cancer, likely via the transcriptional repressor EZH2 regulation." (PMID 38542512, 2024). "The direct regulation of EZH2 on SFRP1 in osteoarthritis and laryngeal carcinoma has been reported before." (PMID 38566211, 2024). "In our study, the proportion of EZH2-expressing cells was the highest in the subpopulation with the worst prognosis (hypopharyngeal carcinoma patients) and the lowest in those with the best DFS rates (laryngeal carcinoma patients)." (PMID 38791289, 2024). "EZH2 also inhibits the expression of RUNX3 in bile duct carcinoma and laryngeal carcinoma." (PMID 33718109, 2020).